STAT3 (signal transducer and activator of transcription 3)
Diseases named in the same sentence as STAT3 in open-access papers (continued):
Sharing a sentence is not in itself a finding about the gene and the disease.
cancer (continued). "Interestingly, a large number of proteins upregulated in the proteome of EIF3F-overexpressing cells belong to the β-catenin signaling pathway, and recent studies revealed that STAT3 cooperates with β-catenin via direct physical interaction to promote cancer cell malignancy and chemoresistance." (PMID 31527668, 2020). "In addition, our data suggests that indirect targeting of STAT3 may be a feasible way to reduce constitutively active STAT3 in cancers instead of direct STAT3 inhibition." (PMID 32231398, 2020). "Interestingly, several pro-inflammatory cytokines, acting in an autocrine fashion on cancer cells, besides STAT3, may activate other pro-oncogenic pathways such as mTOR, crucial for cancer survival." (PMID 32754441, 2020). "However, collectively, studies suggest that the restoration of STAT3-inhibited autophagy may represent an important mechanism for cancer treatment." (PMID 32722030, 2020). "Activated STAT3 protein lead to the transcription of various downstream target genes such as IL-17, IL-23, BCL-XL, BCL-2, MCL1, cyclin D1 (CCDN1), c-MYC, and vascular endothelial growth factor (VEGF) that control essential pro-carcinogenic, inflammation-associated networks during cancer progression." (PMID 33584695, 2020). "However, we observed an opposite expression in AT compared to cancer cells, suggesting a different role of this lncRNA in visceral adipocytes, that could potentially involve H19 target genes STAT3 and SPARC." (PMID 32714872, 2020). "Thus, aberrant activation of STAT3 can activate Bcl-2 family proteins in various cancer cells." (PMID 32872659, 2020). "One significant example of this crosstalk between cancer cells and the microenvironment is the secretion of cytokines like interleukin-6 (IL-6) by the cancer-associated mesenchymal stem cells that enhance the progression of CRC through the IL-6/JAK2/STAT3 signaling." (PMID 32626705, 2020). "Importantly, the epithelial lesions are preceded by enhanced activation of cytoplasmic and nuclear NF-κB promoting significant molecular alterations of cancer-related genes, such as Bcl2, Egfr, Stat3, Tnf, and Il6, and miRNA markers, such as miR-21, miR-155, miR-192, miR-375, miR-451a, and miR-34a." (PMID 32344873, 2020). "In addition to its role within the nucleus to potentiate survival, proliferation, and metastasis through transcriptional activity, cytoplasmic STAT3 also affects cancer cells by controlling metabolism, immune evasion, angiogenesis, and programmed cell death via non-transcriptional regulation." (PMID 32722030, 2020). "Hence, this provides further evidence for IL6 and STAT3 being viable targets for cancer therapy." (PMID 31936675, 2020). "Notably, STAT3 activity in TAMs seems to promote tumorigenesis and therapeutic resistance by supporting the persistence of a population of cancer cells with increased tumorigenic potential, known as cancer stem/initiating cells." (PMID 33584695, 2020). "However, the functions of STAT3 in immune and drug response in cancer remain elusive." (PMID 32486001, 2020). "However, the efficacy of our platform against human cancers is unknown, and maximal dosing of STAT3 decoy was limited by the loading capacity of the lipid cationic microbubbles used in our prior study." (PMID 33206698, 2020). "In addition to PTPs, various negative regulators of STAT3 signaling in cancer cells are known." (PMID 31900385, 2020). "Therefore, we conclude that STAT3 is a key signaling regulator of cancer metabolism." (PMID 33003453, 2020). "Besides, STAT3 also promotes angiogenesis, invasiveness and immunosuppression in cancer." (PMID 32733808, 2020). "Since increased activation of STAT3 is observed in a wide variety of cancer cells, and it regulates downstream channels to promote survival and growth, researchers have pointed out STAT3 as a promising molecular target for therapeutic intervention in cancer patients." (PMID 32722030, 2020).
cancer (continued). "Therefore, STAT3 is considered an important therapeutic target for several reasons, including its role in suppressing cancer cell apoptosis and in multiple oncogenic pathways, such that its inhibition would effectively block the action of several upstream tyrosine kinases." (PMID 33206698, 2020). "STAT3 maintains an abnormal activation state, which can accelerate the cycle process by controlling the protein levels of cyclin D, p21, and p27, promoting the new blood vessels generation and providing supplementary nutrition for the development of cancer cells." (PMID 32849902, 2020). "Thus, recent studies have been focused on the suppression of STAT3 activity for cancer treatment." (PMID 33260759, 2020). "The analysis of transcriptome sequencing implied that activation of STAT3 signaling pathway by downregulated miR-337-3p might be a potential mechanism to induce epithelial to mesenchymal transition (EMT) of cancer cell and promote metastasis under chronic stress." (PMID 32934214, 2020). "In addition, STAT3 is well known for its immunomodulatory activity in cancer." (PMID 31947933, 2020). "Signal transducer and activator of transcription 3 (STAT3) is constitutively activated in different human cancers and it regulates a set of genes implicated in cancer cell survival, proliferation, metastasis and drug resistance, hence, it is a powerful cancer therapeutic target." (PMID 32674429, 2020). "In addition to angiogenesis, the STAT3 signaling pathway can regulate EMT in cancer cells." (PMID 32545648, 2020). "Thus, the STAT3 pathway is an important therapeutic target for cancer treatment." (PMID 31929760, 2020). "Targeting the mitochondrial function of STAT3 induces mortality homeostasis, leading to a synthetic lethality effect in glucose-depleted cancers cells by inhibiting complex I, which could be used in cancer chemotherapy." (PMID 33158194, 2020). "STAT3 protein expression levels might diverse in different cancer types." (PMID 32486001, 2020). "In total, the results turned out that some natural compounds might regulate STAT3 in cancer." (PMID 32486001, 2020). "In addition, increased STAT3 levels in cancer contribute to chemoresistance and poor prognosis." (PMID 33081075, 2020). "In addition, similar to combined therapy, certain bifunctional compounds are emerging and may represent a new generation of highly efficacious STAT3 inhibitors for cancer therapy in the future." (PMID 32972405, 2020). "Therefore, our findings suggest that EIF3F could be considered as a novel effector of cell migration and metastasis, and its molecular link with STAT3 fosters the need to pursue investigations on the role of the EIF3F–STAT3 signaling in cancer." (PMID 31527668, 2020). "Signal transducer and activator of transcription 3 (STAT3) is thought to play a key role in regulating CSCs in several types of cancer and is involved in a number of cell signaling pathways implicated in cancer cell survival, proliferation, metastasis, and angiogenesis." (PMID 32236642, 2020). "In addition, as STAT3 is a well-known oncogene often overexpressed or activated in cancer, impairment in its expression could be a promising strategy toward cancer progression." (PMID 32230926, 2020). "Finally, C/EBPδ mRNA can be overexpressed in cancer cells expressing high levels of STAT3." (PMID 32560326, 2020). "Chronic inflammation mediated via NF-κB and STAT3 is inhibited by NF-κB negative regulatory proteins (A20 and Cyld) and STAT3 negative regulatory (SOCSs) proteins to prevent chronic inflammation-induced autoimmune diseases and cancers and to restore homeostasis and tissue repair." (PMID 33182552, 2020).
cancer (continued). "Furthermore, functional experiments demonstrated that the effect of knockdown BECN1 on cancer cells was reversed by genetic or pharmacological inhibition of STAT3, strongly indicating that BECN1 is involved in CRC metastasis through regulation of STAT3 phosphorylation in CRC." (PMID 32358527, 2020). "Moreover, STAT3 is a major intrinsic pathway for cancer inflammation." (PMID 32863742, 2020). "Therefore, targeting STAT3 may have a double beneficial effect, as it can act on both cancer and immune cell side." (PMID 32754441, 2020). "Notably, although co‐cultured CM significantly increased the level of phospho-STAT3 in MIA PaCa-2 and AsPC-1 cells targeted by the scrambled siRNA, cancer cells targeted by two STAT3-specific siRNAs exhibited impaired phospho-STAT3 induction following co-cultured CM treatment." (PMID 32308766, 2020). "Therefore, STAT3 is a very attractive target for the therapy of various cancers, including HCC6." (PMID 31980595, 2020). "Importantly, STAT3 involves in regulating key metabolism pathways in normal and cancer cells." (PMID 32022328, 2020). "The current study’s findings suggest that curcumin synergistically enhances the anticancer activity of cisplatin in PTC cells as well as in cancer stem-like cells by targeting STAT3, which suggests that curcumin combined with chemotherapeutic agents may provide better therapeutic outcomes." (PMID 31936675, 2020). "In addition, STAT3 inhibitors are currently in clinical trials for the treatment of many cancers." (PMID 31947933, 2020). "Considering that the IL-6R/JAK/STAT3 pathway is aberrantly hyperactivated in >70% of cancers, it would be interesting to determine if impairing the palmitoylation of STAT3 with the use of phytochemicals would prove to be successful in hampering cancer cell growth." (PMID 32731620, 2020). "In addition, STAT3 was another downstream target of PTPRS in cancer progression." (PMID 33163494, 2020). "In this study we demonstrate that inhibition of activated STAT3 by GL can decrease the viability of docetaxel-resistant and patient-derived spheres retaining stemness characteristics, indicating that this is a promising approach to target the cancer stem cell niche in PCa." (PMID 32811873, 2020). "STAT3 and nuclear factor kappa B (NF-κB) signaling pathway can be activated by inflammatory responses which may mediate survival-favoring signaling and induce metabolic reprogramming, driving cancer cell growth, migration, and invasion." (PMID 32596159, 2020). "It was also possible that ESI-09 might exert its anti-cancer action through extramitochondrial deterioration since some mitochondrial uncouplers have been shown to inhibit several oncogenic pathways, such as Wnt/β-catenin, mTORC1, STAT3, and Notch." (PMID 33007425, 2020). "EMT is the binding of epithelial cells with mesenchymal cancer-associatedfibroblasts (CAFs), which results in loss of adhesion among cells, causing tumorprogression.In cancers mediated by STAT-3, EMT gets involved in cancer progression by theIL-6 and JAK-STAT-3 pathway." (PMID 32167126, 2020). "In addition, studies have found that ATP can directly pass through receptors other than P2 × 7 receptor (such as P2Y2 receptor), or indirectly through stimulation to induce the production of invasive molecules mediated by STAT3, thereby promoting the diffusion of cancer cells." (PMID 33330466, 2020). "Thus, STAT3 signaling has been chosen as cancer therapeutic target." (PMID 32351887, 2020).
cancer (continued). "Furthermore, in comparison with cancer cells, non-cancerous cells are not sensitive to loss of STAT3 function." (PMID 31980595, 2020). "Thus, STAT3 and NF-κB can be considered as potent target molecules for cancer therapy." (PMID 31248140, 2019). "Interestingly, Rack1 is also involved in the activation of STAT3 in several cancer cells." (PMID 31113450, 2019). "In addition, the down-regulation of STAT3 gene may be effective in the prevention of DTX resistance in cancer therapy." (PMID 30041514, 2019). "Thus, this newly-discovered Nanog-Stat-3-regulated miR-21 signaling pathways during HA-CD44 interaction may be considered as another new drug target to treat cancers." (PMID 31293964, 2019). "Therefore, STAT3 has been validated as a novel anti-cancer drug target and the strategies targeting HCC CSCs may bring new hopes to HCC therapy." (PMID 30709346, 2019). "Also, inhibition of STAT3 activation was shown to reduce cancer stemness and sphere formation." (PMID 30944375, 2019). "Therefore, blocking STAT3 activity in cancer is of particular interest." (PMID 31752278, 2019). "To test this hypothesis, we examined the changes in phospho-STAT3 in cancer cells." (PMID 31818309, 2019). "Hence, the observations here that IL-15C-drives STAT3 activation in NK cells and their production of IL-10 may indicate that targeting of NK cells in this context could reduce the efficacy of anti-cancer IL-15C therapy or at least limit NK cell cytotoxicity." (PMID 31552035, 2019). "Importantly, the treatment of cancer cells with TGFβ directly had mild effect on STAT3 activation." (PMID 31609088, 2019). "Achieving a more complete picture of the spectrum of events that lead to dysregulated STAT3 signaling in T cell malignancies and the precise molecular consequences of the augmented STAT3 signal may enable development of future therapeutic modalities for STAT3 driven cancers." (PMID 31684088, 2019). "Therefore, inhibition of the STAT3 pathway by butyrate in cancer could lead to both increased cell death and decreased angiogenesis." (PMID 31067776, 2019). "However, under pathological conditions activated STAT3 has been implicated in hematological and non-hematological tumors, largely through promotion of autocrine IL-6 signaling and secretion that drives cancer progression and multidrug resistance." (PMID 31105556, 2019). "Furthermore, aberrant STAT3 expression may play a role in maintaining survival and plasticity of cancer stem cells, as STAT3 is known to support pluripotency by upregulating sox2 [SRY-box 2], Nanog [Homeobox protein nanog], and c-myc [MYC proto-onco gene]." (PMID 31105556, 2019). "Additionally, STAT-3 inhibits the proinflammatory effects of NF-κB signaling molecules, such as IL-12 in DCs, while it can also bind to NF-κB complexes to upregulate inflammatory genes, enhancing cancer progression." (PMID 31698775, 2019). "Interestingly, STAT3 activation seems to be a general mechanism of acquired resistance since it was also observed in cancer cells driven by diverse kinases, including EGFR, HER2, ALK, and MET, as well as mutant KRAS following treatment with specific inhibitors." (PMID 30622697, 2019). "Thus, identifying effective STAT3 inhibitor molecules that could revert the Sor resistance to develop individualized therapeutic strategies for clinical application in cancer is a need." (PMID 31619257, 2019). "This differential cytotoxicity mediated through inhibition of STAT3 activation in cancer cells while providing antioxidant protection to healthy cells suggests that antioxidant-conjugated diarylpentanoids would be useful as safe anticancer agents for cancer therapy." (PMID 31295798, 2019). "Therefore, the use of molecules able to reduce STAT3 activation and, on the other hand, to induce a mild oxidative stress in a high-reduced cellular environment may potentially improve cancer treatment outcome." (PMID 31781335, 2019).
cancer (continued). "Considering STAT3 involvement in promoting mitochondrial functions which are needed for cancer cell stemness and metabolic reprogramming, cancer cells that bypass senescence and acquire stem cell properties are sensitive to depletion and/or inactivation of STAT3." (PMID 30857125, 2019). "Thus, STAT3 is considered a valid therapeutic target for cancer therapy." (PMID 30691132, 2019). "Furthermore, STAT3-depleted DCs are more resistant to cancer cell-derived inhibitory factors." (PMID 31296257, 2019). "According to the recent discovery that STAT3 inhibitors may improve the outcome of chemotherapy in cancer patients, it is tempting to speculate that the supporting role of progranulin on STAT3 activity might be the reason, or among the reasons, underlying such an effect." (PMID 31361391, 2019). "Lipophilic antipsychotic drugs, known to cross the BBB effectively to bind to central dopamine D2 receptors and promote their therapeutic action, are able to modulate many cancer-associated intracellular signaling pathways, such as PI3K-AKT-mTOR, STAT3, and WNT, and may act as anti-cancer drugs." (PMID 31480389, 2019). "This differential pattern of expression suggests that in UBC STAT3 activation might rely on genomic and epigenetic abnormalities (limited to cancer cells) as well as on ligand dependent activation of cytokine and growth factor receptors (on cancer cells and cells of the microenvironment)." (PMID 31438567, 2019). "Thus, in the light of all these evidences suggesting that STAT3 and STAT5A play critical roles in cancer progression, the present study investigated the nature and extent of the involvement of STAT3 and STAT5A in the therapeutic response and disease progression of patients with GBM." (PMID 31783691, 2019). "STAT3 activation could promote the expression of gene products required for cell-cycle regulators, inhibitors of apoptosis, and inducers of angiogenesis, resulting in increased proliferation and decreased apoptosis in various cancer cells." (PMID 30872582, 2019). "Among these pathways, STAT3 pathway has been identified as a key regulator of cancer stemness properties and is involved in the ability of CSCs to survive, self-renewal, metastasize, evade the immune system, resist conventional cancer therapies, and lead to eventual cancer recurrence." (PMID 30709346, 2019). "Therefore, targeting the downstream effectors of STAT3 with more narrow activities might increase the likelihood of developing an efficient anti-cancer drug." (PMID 31551419, 2019). "Oncogene expression in GB cells and defective signaling in the immune cells of TME may contribute to persistent phosphorylation of STAT3 at tyrosine-705 (Tyr-705) and/or serine-727 (Ser-727) that enhances glial cell transformation, affects cell metabolism and promotes survival of cancer cells." (PMID 31698775, 2019). "Thus, STAT3 is widely recognized as a promising therapeutic target in cancer treatment." (PMID 31456939, 2019). "In addition to its role in cancer cells, STAT3 also plays a pivotal role in the immune system." (PMID 31088482, 2019). "Modalities for targeting STAT3 in cancer may be classified into direct and indirect approaches." (PMID 31130718, 2019). "Therefore, small molecules, such as PROTACs that can induce STAT3 protein degradation may be used more efficiently in combination with current inhibitors for cancer therapy." (PMID 31088482, 2019). "Consequently, STAT3 is considered as a target for cancer therapy." (PMID 31766350, 2019). "Blockage of STAT3 signaling pathway may lead to growth inhibition and apoptosis in cancer cells." (PMID 30541589, 2018). "However, this approach is limited by the lack of a single STAT3 driver kinase in many cancer cells as well as by the development of resistance mutations in the targeted kinase or activation of other upstream kinases with redundant activities." (PMID 29914167, 2018).